STAT3 (signal transducer and activator of transcription 3)
Diseases named in the same sentence as STAT3 in open-access papers (continued):
Sharing a sentence is not in itself a finding about the gene and the disease.
melanoma (continued). "Inhibition of PI3K/AKT or STAT3 pathway partially abolished the promotion of melanoma malignancy induced by TRIM14 overexpression." (PMID 33982666, 2021). "In summary, we conclude that CIRT can reduce the population of MDSC through a JAK2/STAT3-dependent signalling pathway, boost anti-tumour immune responses, and reduce tumour growth, therefore, increasing the overall survival of the melanoma-bearing mice." (PMID 34732697, 2021). "MDA-7/IL-24 protein induced phosphorylation and nuclear translocation of STAT3 in melanoma cells via both type 1 and type 2 IL-20R and induced dose-dependent cell death in melanoma tumor cells." (PMID 35008495, 2021). "Immune-competent C57BL/6 mice were intravenously challenged with the mouse B16 melanoma cells, followed by i.v. injection of PS-unacet.-STAT3, PS-STAT3-K685R, and PO- or PS-acet.-STAT3 peptides, as well as vehicle." (PMID 33491667, 2021). "To determine the clinical significance of the STAT3 gene, we performed STAT3 expression in TCGA melanoma datasets." (PMID 33936081, 2021). "Together, these studies show that elevated S100B suppresses IL6 and STAT3 transcriptional activity in malignant melanoma." (PMID 34411141, 2021). "Collectively, these data continue to support a mechanism in which elevated S100B found in malignant melanoma negatively regulates the IL6/STAT3 pathway and that functional IL6 can be restored when S100B expression is inhibited." (PMID 34411141, 2021). "We analyzed the co-expression of Tim-3 and PD-1 with STAT3 in the melanoma patients and the Treg cells." (PMID 33936081, 2021). "To examine the influence of STAT3 downregulation upon the anti-tumor immune response, we analyzed tumor-infiltrated lymphocytes that were studied in melanoma mice." (PMID 33936081, 2021). "Overexpression of TRIM14 significantly promoted growth and clone formation capacity of melanoma cells, while blocking AKT or STAT3 pathway partially reversed the promotion of melanoma cell proliferation mediated by TRIM14." (PMID 33982666, 2021). "Mechanistically, the manifestation of STAT3 decreases the expression of Tim-3 and various cytokines in the purified Treg cells from individual PBMCs and the murine melanoma model, limiting the immunosuppression of Treg cells." (PMID 33936081, 2021). "To determine the impact of STAT3 downregulation on anti-melanoma immune response, we analyzed the cell phenotype and cytokine expression pattern in spleen tissue using flow cytometry." (PMID 33936081, 2021). "Targeting STAT3 significantly boosts the response of resistant-PD-1 therapy within the melanoma mouse model." (PMID 33936081, 2021). "Under these conditions, STAT3 downregulation significantly increased the anti-PD-1 efficacy in melanoma." (PMID 33936081, 2021). "It has been shown that NEDD9 acted through SRC and STAT3 to promote invasion in melanoma, cervical cancer, and ovarian cancer." (PMID 34314382, 2021). "Altogether, these results demonstrated that CD27-AS1-208 exerted its facilitative role in melanoma progression by activating STAT3." (PMID 35096622, 2021). "Overall, these data confirm the in vitro observation and suggest the induction of IL‐6/STAT3 following NLRP3 inflammasome activation as an integral driver of melanoma progression." (PMID 34531850, 2021). "Altogether, these results strongly confirmed that STAT3 downregulation dampened Treg function in melanoma, enhanced the anti-tumor immunity." (PMID 33936081, 2021). "miR-204 is regulated by STAT3 and its transcript levels are increased in amelanotic melanoma cells, where it functions as a mediator of anti-migratory effects of vemurafenib by modulating expression of AP1S2." (PMID 33968718, 2021). "PEAK1 promotes tumorigenesis and metastasis via activating JAK/STAT3 signals, and PEAK1 knockdown reduced tumorigenesis and metastasis in melanoma via inactivating JAK/STAT3 signals, providing a novel therapeutic strategy for melanoma treatment." (PMID 34365903, 2021).
melanoma (continued). "On the contrary, PEAK1 overexpression promotes JAK/STAT3 signaling, thereby increasing melanoma cell invasion, migration, and proliferation." (PMID 34365903, 2021). "A significant increase for tumor cell necrosis in melanoma was observed in the STAT3 inhibitor group with anti-PD-1 therapy, indicating excellent therapy efficacy." (PMID 33936081, 2021). "A certain level of pSer-STAT3 (either constitutive or inducible) seems to be essential for the optimal canonical function of STAT3 in melanoma cells." (PMID 34884773, 2021). "Notwithstanding, these results show that TLR4 signaling in melanoma cells increases the secretion of immunosuppressive cytokines that can be upregulated by STAT3." (PMID 32312954, 2020). "Activation/phosphorylation of STAT3 leads to the transcription of a panel of genes involved in melanoma growth, angiogenesis, metastasis and immune evasion." (PMID 32312954, 2020). "Another study showed that high expression of G6PD promotes melanoma growth via the signal transducer and activator of transcription 3/5 (STAT3/5) pathway in a human melanoma xenograft model." (PMID 33091721, 2020). "It has also been demonstrated that the BCL-XL level was positively correlated with the level of active STAT3 in melanoma." (PMID 32466509, 2020). "In conclusion, these data bring new evidence of the potential tumorigenic role of STAT3 in NRAS-mutant melanomas and will help improving current therapy strategies for this particular patient group." (PMID 31906480, 2020). "Overall, the in vivo experiment suggested that a VA-induced decrease of melanoma weight is closely related to STAT3 activation and consequent regulation of apoptosis and autophagy." (PMID 32722030, 2020). "The constitutive activation of MAPK pathway along with STAT3 pathway plays an essential role inducing the immune evasion by melanoma cells." (PMID 32054102, 2020). "To determine the correlation of TLR4 expression and STAT3 activation/phosphorylation, we took advantage of the human melanoma tissue microarray (a total of 208 samples) and performed immunohistochemical staining." (PMID 32312954, 2020). "In this notion, we have conducted a comorbidity model by feeding C57BL6 mice with an HFD, followed by an allograft of melanoma, and investigated the effect of VA in regards of STAT3-related mechanisms." (PMID 32722030, 2020). "In the current study, two human melanoma cell lines A375 and A2058 with constant STAT3 activation were used for studying the anti-melanoma activities of shikonin and the involvement of STAT3 in these effects." (PMID 32536866, 2020). "Forth, we found that overexpression of a dominant negative STAT3 variant in melanoma cells reverses LPS-provoked tumor growth, angiogenesis and EMT and reprograms melanoma microenvironment in mice." (PMID 32312954, 2020). "IL-6 plays a central role in melanoma development and enhances the IL-10 production via STAT3-dependent signaling." (PMID 32508531, 2020). "We found increased levels of phosphorylated STAT3 following induction of BRN2 expression in three of three melanoma cell lines." (PMID 32632141, 2020). "Results showed that both parthenolide and TAK-242 dose-dependently lowered protein levels of TLR4, STAT3 and phosphorylated STAT3 in and inhibited the proliferation of A375 and B16 melanoma cells." (PMID 32312954, 2020). "Another example of targeted delivery was the delivery of STAT3 siRNA for the treatment of melanoma by dissolving polyethylenimine MNs." (PMID 32850709, 2020). "Several cytokines and inflammatory factors induce phosphorylation of STAT3, which in turn increases survival and metastatic potential in melanoma." (PMID 32722030, 2020). "TLR-4 signaling involves the activation of signal transducer and activator of transcription 3 (STAT3), which on turn promotes melanoma growth and aggressiveness associated features including angiogenesis and epithelial to mesenchymal transition." (PMID 33193402, 2020).
melanoma (continued). "In this study, we showed that MPLAs activates STAT3 in melanoma cells, promotes melanoma cell proliferation, invasion and immunosuppressive cytokine secretion, and enhances pro-angiogenic effects of melanoma cells." (PMID 32312954, 2020). "In this study, we demonstrated that activation of TLR4/MYD88/STAT3 and TLR4/TRIF/STAT3 pathways promotes proliferation of cultured melanoma cells." (PMID 32312954, 2020). "The changes of immune cell profiles imply that activation of STAT3 contributes to TLR4 signaling-mediated immunosuppression in melanoma microenvironment." (PMID 32312954, 2020). "Our results support such a notion, since decreased melanoma weight by treating VA was a result of regulated STAT3." (PMID 32722030, 2020). "Inappropriately and persistently activated STAT3 have been estimated to occur in approximately 70% of hematopoietic and solid malignancies, including melanoma." (PMID 32536866, 2020). "Taken together, STAT3 activation via HER3 seems to be a mechanism that melanoma cells adapt to escape from targeted therapies." (PMID 33327495, 2020). "Inhibiting the activation of STAT3 and STAT3-targeted immunosuppressive cytokines; increasing recruitment of DCs to melanoma tissues and spleens to enhance immune response." (PMID 32733246, 2020). "Results showed that both LPS and MPLAs, two TLR4 ligands, increased the phosphorylation of STAT3 in multiple melanoma cell lines." (PMID 32312954, 2020). "Another promising target for melanoma therapy is signal transducer and activator of transcription 3 (STAT3), which has an important role in tumor cell proliferation, survival, invasion and immunosuppression." (PMID 32059541, 2020). "Next, we analyzed the phosphorylation of HER3 and STAT3 on the protein level after the treatment of A375 and SK Mel 28 melanoma cells with vem or DMSO at different time points." (PMID 33327495, 2020). "In this study, our findings provide evidence that STAT3 is a key player in TLR4 signaling-mediated melanoma progression." (PMID 32312954, 2020). "Signal transducer and activator of transcription 3 (STAT3) signaling promotes melanoma development and progression, which has been validated as an effective target in melanoma treatment." (PMID 32536866, 2020). "We can collect additional patient melanoma samples to study the roles of gene polymorphisms of TLR4, MYD88, TRIF, and STAT3 in melanomagenesis in the future." (PMID 32312954, 2020). "Signal transducer and activator of transcription 3 (STAT3) has been identified as a major oncogene in melanoma progression." (PMID 32312954, 2020). "Consistently, STAT3 level was higher in melanoma samples and it supported maintenance of melanoma CSCs." (PMID 33390934, 2020). "Stat3 is one of the seven members of the STAT family continuously activated in various tumors including melanoma, and executes an essential role in multiple biological processes, such as cell proliferation, differentiation and immune responses." (PMID 32565740, 2020). "Recent studies suggest that HIF1α is regulated by STAT3 as the later increases the half-life of the transcription factor in both human and mouse melanoma cells." (PMID 32211322, 2020). "In this study, we found that knockdown of TLR4 not only inhibits STAT3 activation, but also induces STAT3 protein degradation, suggesting an alternative approach to blocking STAT3 signaling in melanoma: genetically or pharmacologically inhibiting TLR4." (PMID 32312954, 2020). "It was found that protein level of phosphorylated STAT3 and transcriptional activity of STAT3 were higher in A375CA-TLR4 cells than in A375NC cells, indicating that constitutive activation of TLR4 enhances STAT3 activation in melanoma cells." (PMID 32312954, 2020). "We also found that activation of STAT3 is a key event in TLR4 signaling-mediated melanoma development." (PMID 32312954, 2020). "Overall, this study demonstrates that activation of STAT3 is a critical event in TLR4 signaling-mediated melanoma progression." (PMID 32312954, 2020).
melanoma (continued). "The elevated STAT3 expression causes an increase in the expression of SRY-Box Transcription Factor 2 (SOX2), which is an important factor in melanoma cell resistance." (PMID 33327495, 2020). "The results of IHC staining imply an important role of STAT3 activation in TLR4 signaling-mediated melanoma growth, angiogenesis and EMT." (PMID 32312954, 2020). "Taken together, these data suggest that decreased production of IL-6 in ATF3-overexpressing HDFs contributes to inhibition of melanoma cell proliferation and migration by blocking the STAT3 pathway." (PMID 32373541, 2020). "Protein levels of TLR4 and phosphorylated STAT3 (Y705) were significantly elevated in melanoma tissues compared to that in normal tissues, a finding consistent with previous reports." (PMID 32312954, 2020). "We found that the blockade of STAT3 activation made melanoma cells more sensitive toward the inhibitor treatment." (PMID 33327495, 2020). "The same research team later conjugated the AuNPs with imatinib, forming a co-delivery system, STAT3-siRNA–AuNPs and imatinib–AuNPs, which generated higher apoptosis in melanoma cells." (PMID 31979325, 2020). "In the tissue microarray analyses, we found that TLR4 expression and STAT3 phosphorylation are positively correlated in melanoma tissues." (PMID 32312954, 2020). "Parthenolide also downregulates protein levels of TLR4, STAT3 and phosphorylated STAT3 in tumor tissues and impedes tumor growth in melanoma-bearing mice." (PMID 32312954, 2020). "Constitutive activation of STAT3 has been observed in a variety of tumors, including melanoma and lung, pancreatic, colorectal and ovarian cancers." (PMID 31124056, 2020). "STAT3 is well recognized for favoring melanoma development and progression by regulating several genes." (PMID 32536866, 2020). "STAT3 inhibitors that are being used in clinical trials exert anti-melanoma effects by inhibiting STAT3 activation." (PMID 32312954, 2020). "Stat3 is a well-known substrate of Fyn and plays crucial role in melanoma tumorigenesis; thus, Stat3 acts as a substrate to test Fyn protein kinase activity." (PMID 32565740, 2020). "Potentially, CD24 expression was mediated by STAT3-dependent /SOX2-mediated pathways that was correlated with adaptive resistance toward targeted therapy in melanoma." (PMID 33196458, 2020). "The observation that knockdown of MYD88 abolishes MPLAs-enhanced STAT3 phosphorylation suggests that TRIF can be regulated by MYD88 in melanoma." (PMID 32312954, 2020). "STAT3 is emerging as an important therapeutic target for melanoma, owing to its key role in promoting metastasis, angiogenesis, immune evasion, and stemness." (PMID 32340351, 2020). "Third, we found that constitutive TLR4 signaling enhances STAT3 activation in melanoma tissues and promotes tumor growth, angiogenesis and epithelial–mesenchymal transition (EMT) in mice." (PMID 32312954, 2020). "Together, these data indicate that activation of TLR4 enhances STAT3 activation in melanoma tissues and promotes tumor growth, angiogenesis and EMT in mice." (PMID 32312954, 2020). "First, we found that TLR4 expression and STAT3 activation are positively correlated in human melanoma tissues." (PMID 32312954, 2020). "In primary melanocytes NRASQ61 is able to override OIS through activation of the STAT3 pathway, whereas in immortalized melanocytes and melanoma cell lines, NRASQ61 promotes a more tumorigenic behavior." (PMID 31906480, 2020). "Of note, some of these cytokines are known activators of STAT3 signaling (IL-8, IL-1β and IL-24), which is protumorigenic and favors melanoma reprogramming towards a tumor-initiating phenotype." (PMID 31906480, 2020). "Herein, we show that RNAi mediated silencing of STAT3 expression in the tumor tissue robustly inhibit tumor growth in B16F10 mouse model of melanoma." (PMID 32059541, 2020). "The anti-melanoma activity of shikonin is at least partially attributed to the inhibition on STAT3 signaling." (PMID 32536866, 2020).
melanoma (continued). "Neither the treatment with recombinant BTC nor that with NRG1 and NRG2 altered the activation of HER3 and STAT3 in A375 melanoma cells." (PMID 33327495, 2020). "We found that BCL2L10 is expressed in both melanoma cell lines and patients and that its transcription is regulated by STAT3." (PMID 33396645, 2020). "Analyzing the expression of known STAT3 target genes in different melanoma cell lines upon vem treatment, we found a significant reduction of the expression levels of most genes; in contrast, SOX2 expression was significantly upregulated." (PMID 33327495, 2020). "In this study, we established TLR4/MYD88/STAT3 and TLR4/TRIF/STAT3 pathways in melanoma and demonstrated their pathogenic roles." (PMID 32312954, 2020). "To further determine the involvement of STAT3 in shikonin-mediated anti-melanoma action, we overexpressed STAT3 in A375 cells by transiently transfected with a constitutively active STAT3 plasmid or an empty vector (EV)." (PMID 32536866, 2020). "Similarly, we also observed a decreasing level of Bcl-2 in Fyn deficiency and Lj-1-60 treated melanoma cells, which may explain why inactivated Stat3 cannot translocate into the nucleus and bind to the Bcl-2 promoter, thus decreasing the transcription of Bcl-2." (PMID 32565740, 2020). "Quercetin also inhibited STAT3 transcription activity and target genes that are involved in cell growth, migration, and invasion in melanoma A375 and A2058 cells and inhibited murine B16F10 cells lung metastasis in vivo." (PMID 32521759, 2020). "TLR4 signaling activates STAT3 through MYD88 and TRIF, and subsequently upregulates a series of STAT3 target genes to promote melanoma progression." (PMID 32312954, 2020). "It has been reported that constitutive activation of the STAT3 signaling pathway promotes melanoma cell growth, survival, migration, invasion, and allows cancer metastasis." (PMID 32536866, 2020). "In this COC cell model, VA treatment successfully repressed STAT3 activation, in turn inducing the apoptotic and autophagic pathway in melanoma cells." (PMID 32722030, 2020). "These in vivo results, along with similar observations in the VA-treated COC vitro model, sufficiently showed the inhibition of STAT3 by VA treatment subsequently led to the induction of autophagy of B16BL6 melanoma cells." (PMID 32722030, 2020). "This study aims to evaluate the anti-melanoma activities of shikonin and explore the involvement of STAT3 signaling in these effects." (PMID 32536866, 2020). "The formulation provided higher stability and higher cellular uptake by tumor cells with the aid of clathrin-mediated endocytosis and, furthermore, inside the tumor cell, siRNA repressed the overexpression of STAT3 protein, favoring melanoma cell destruction." (PMID 31979325, 2020). "Increased expression of the anti-apoptotic protein BCL-XL is positively correlated to melanoma progression and phosphorylated STAT-3 (pSTAT-3)." (PMID 30870978, 2019). "Graphene oxide was functionalized with PEI and polyethylene glycol (PEG) to serve as a plasmid based Stat3 siRNA carrier in the in vivo study of treating mouse melanoma cell line." (PMID 30847297, 2019). "A similar modulatory effect on MMP-2 and VEGF expression has been recently reported for OC in melanoma cells, via the suppression of STAT3 transcriptional pathway." (PMID 31766503, 2019). "In a murine melanoma model, BMDCs transfected with STAT3 siRNA by lipopolyplexes enhanced the maturation of DCs; the secretion of TNF-α, IFN-γ, and IL-12; and the proliferation of allogenic T cells." (PMID 30658461, 2019). "Flavonoids modulate inflammatory effects through a few key mediators in melanoma and skin tissues: AP-1, NFkB, STAT3 and nitric oxidases (mainly iNOS and nNOS)." (PMID 31139235, 2019). "In a murine melanoma model, the combination of oral administration of bacteria-transformed surviving DNA vaccine and intravenous administration of STAT3 shRNA induced synergistic effect." (PMID 30658461, 2019).